HMGB1 (high mobility group box 1)
Diseases named in the same sentence as HMGB1 in open-access papers (continued):
Sharing a sentence is not in itself a finding about the gene and the disease.
Sepsis (continued). "At a critical concentration of 15.27 ng/mL, HMGB1 demonstrates a 100% sensitivity and an 83.33% specificity in predicting the prolonged ICU stay of sepsis patients for more than five days, achieving an AUC of 0.958." (PMID 39201697, 2024). "Interleukin (IL)-1β, tumour necrosis factor (TNFα), high mobility group protein 1 (HMGB1) and IL-6 are the most vital cytokines promoting the inflammatory response in sepsis and are key biomarkers of septic shock in systemic inflammatory response syndrome." (PMID 37474902, 2023). "Therefore, the regulation of HMGB1 may be a potent therapeutic method in sepsis." (PMID 38026444, 2023). "Biomarkers such as High Mobility Group Box1 (HMGB-1) and TGF-beta 1 have emerged as promising candidates for further investigation in sepsis pathogenesis." (PMID 37626609, 2023). "Platelet-derived exosomal high-mobility group protein 1 (HMGB1) and/or miR-15b-5p and miR-378a-3p promote excessive NET formation through the Akt/mTOR autophagy pathway during sepsis and subsequent organ injury." (PMID 36968817, 2023). "HMGB-1, a most extensively studied DAMPs mediating organ injury during ARDS or sepsis, is increased in severe COVID-19." (PMID 36507222, 2023). "During sepsis, Mφs uptake extracellular lactate via monocarboxylate transporters (MCT) to promote HMGB1 lactylation via a p300/CBP-dependent mechanism." (PMID 37841247, 2023). "In LPS cell models and CLP-induced sepsis mouse models, deacetylation of HMGB1 achieved by activating SIRT1 reduces the release of HMGB1 and sepsis-related mortality." (PMID 37628912, 2023). "The activation of ECs in sepsis is mainly due to the binding of TNF-α and thrombin to TNF receptors and PAR-1, respectively; bacterial LPS and HMGB1 can also play a secondary role." (PMID 36675530, 2023). "The role of the HMGB1-RAGE axis has been demonstrated in the pathogenesis of chronic rhinosinusitis, as well as in sepsis and sepsis-related organ injury, inflammatory skin diseases, rheumatic diseases, or endometriosis." (PMID 37998605, 2023). "Once it is actively secreted by immune cells or the epithelium or released by damaged cells, extracellular HMGB1 can serve as a DAMP and lethal mediator in critical diseases such as sepsis and COVID‐19 in both mice and humans." (PMID 38020710, 2023). "Patients with sepsis show a remarkable increase in the three levels of SII, IL-35 and HMGB-1, which are significantly positively correlated with the disease severity and prognosis of patients." (PMID 36950402, 2023). "In the sepsis mouse model, after PB treatment, a reduction of IL1 β levels, but also high mobility group box 1 (HMGB1) (late intermediate of inflammation), was observed." (PMID 37374085, 2023). "The absence of AMPK in bone marrow cells increases the release of high-mobility group box 1 (HMGB1, a late mediator of inflammation), which in turn leads to the occurrence of sepsis in mice." (PMID 37101253, 2023). "Previous research showed that in sepsis, CIRP adheres to the TLR4/MD2 complex on CD8 + and CD4 + T-cells, resulting in their activation and the production of TNFα and HMGB1 from APCs." (PMID 36920542, 2023). "When HMGB1 is secreted by innate immune cells in relatively low amounts, it binds high-affinity TLR4 receptor to augment inflammation during an early stage of sepsis." (PMID 36735789, 2023). "The increase in HMGB1 in septic mice is the increase in the body’s response to external harmful factors, which is consistent with the previous research results, which means that the therapeutic effect of hydrogen on sepsis may be related to the oxidation reaction system in the animal body." (PMID 36836478, 2023). "NLRP3 inflammasome also promotes the release of high mobility group box 1 (HMGB1), which is involved in endotoxemia and sepsis." (PMID 36142633, 2022). "Upon release, HMGB1 is a prototypical DAMP that plays a decisive role in inflammatory processes and immunosuppression during sepsis and other inflammatory diseases." (PMID 36555168, 2022).
Sepsis (continued). "in sepsis, STS efficiently suppresses inflammatory response in myocardium and reduces myocardial necrosis through markedly reducing production of myocardial HMGB1." (PMID 35720285, 2022). "In addition, NET-derived HMGB1 causes caspase-1 activation and later macrophage pyroptosis through receptor for advanced glycation end products (RAGE) and dynamic-dependent signaling, in which histones play a key role, augmenting inflammatory responses following sepsis." (PMID 36059483, 2022). "In sepsis rat model induced by CLP, circRNA circTLK1 regulates inflammation and oxidative stress through HMGB1, resulting in sepsis-related AKI." (PMID 35720285, 2022). "The compound inhibited HMGB1-mediated hyperpermeability and leukocyte migration in mice, and also decreased CLP-induced release of HMGB1, sepsis-related mortality and tissue injury in vivo." (PMID 36588685, 2022). "naringin decreases TNF-α and HMGB1 release from LPS-stimulated macrophages and improves survival in a CLP-induced sepsis mice." (PMID 35720285, 2022). "In a mouse model of sepsis-induced ALI, blocking HMGB1 or myeloid-specific PTEN KO (PTEN M-KO) increased TGF-β production, inhibited Rorγt and IL-17 expression, and promoted the β-catenin signalling pathway." (PMID 35281010, 2022). "In the studies about HMGs and programmed cell death in sepsis, HMGB1 and HMGA1 induce cell’s apoptosis and pyroptosis, and HMGB1 also induces necroptosis." (PMID 35720285, 2022). "PKM2 also promotes the secretion of the high mobility group box 1 (HMGB1) protein, which mediates immune responses in activated macrophages and has already been identified as a potential therapeutic target in sepsis." (PMID 35596191, 2022). "Increased levels of CAMPs, i.e., cfRNA, cfDNA, histones, extracellular cold-inducible RNA-binding protein (eCIRP), high mobility group box 1 (HMGB1), and ETs in blood have been shown to correlate with disease severity in sepsis." (PMID 35961978, 2022). "Meanwhile, HMGB1, a late-occurring cytokine, can be downregulated by VIP, as proven in mice, and was critical in endotoxemia and sepsis." (PMID 36499231, 2022). "With three Cys residues that can be reduced to thiols, HMGB1 must be in the appropriate redox state to bind to Toll-like receptor (TLR) 4, which participates in sepsis-induced multi-organ failure." (PMID 35596191, 2022). "emodin alleviates sepsis-mediated ALI via inhibition and reduction of NF-kB and HMGB1 pathways mediated by SIRT1." (PMID 35720285, 2022). "However, it is unclear whether lactate could promote HMGB1 release during sepsis." (PMID 34363018, 2022). "In sepsis mice and lipopolysaccharide (LPS)-stimulated cells, activated JAK/STAT signaling promotes HMGB1 acetylation at lysine residues within the NLS, which results in HMGB1 cytoplasmic accumulation and release." (PMID 35632744, 2022). "A clinical study showed that in patients with sepsis, the expression of RIPK3 and MLKL connected with plasma HMGB1 levels, which were related to the severity and mortality of the condition." (PMID 36059483, 2022). "For example, activated PLTs release HMGB1 and PF4 to induce the generation of NETs in thrombotic diseases such as stroke, venous thromboembolism (VTE), and sepsis." (PMID 35869501, 2022). "In the SAP subgroup, HMGB-1 levels were elevated compared to the MAP patients, and were higher than levels expressed in the sepsis cohort." (PMID 36713404, 2022). "In another CLP-induced polymicrobial sepsis model, EA downregulated the level of TNF-α, IL-6, nitrite, and high-mobility group box 1 (HMGB-1) in serum, and reduced nuclear fraction NF-κB p65 activity in the spleen." (PMID 35095910, 2021). "Sepsis also up-regulates the inflammatory cytokines TNF-α, IL-6 and HMGB1 in BV-2 microglia cultures and animals." (PMID 34711216, 2021).
Sepsis (continued). "In this study we have presented results demonstrating that Ts-AES strongly alleviate excessive inflammation via stimulating Tregs response and inhibiting the HMGB1/TLR2/MyD88 signal pathway, and protect mice from ALI induced by sepsis." (PMID 33842398, 2021). "Theacetylation-dependent interaction between HMGB1 and SIRT1 is critical for LPS-induced lethality in an experimental model of sepsis." (PMID 33925132, 2021). "It is therefore plausible that KYNA and its derivatives inhibit NET formation during sepsis through the inhibition of TNF-α and HMGB1 release and IL-1β activation." (PMID 34475875, 2021). "After investigating the effect of circPTK2-miR-181c-5p-HMGB1 in microglia through the previous experiments, we further constructed a CLP-induced sepsis mouse model." (PMID 33952191, 2021). "NR administration prior to sepsis simulation prevents lung and heart damage and improves survival in mice by inhibiting oxidative stress through NAD+/SIRT1 signaling and HMGB1 (plasma high mobility group box-1) release." (PMID 34684434, 2021). "Since an imbalance between the pro- and anti-inflammatory systems is considered to be a vital mechanism of sepsis, we measured the levels of pro-inflammatory cytokines including IL-6, TNF-α, and HMGB1 in the kidneys." (PMID 33936050, 2021). "HMGB1 is one of the specificmarkers of sepsis and it has been suggested to contribute in myocardial injury.Indeed, HMGB is a late mediator of sepsis and its release has been detected after 8h of sepsis." (PMID 33605309, 2021). "Heme treatment or application of CORM-2 significantly reduced plasma levels of HMGB1 in mice challenged with LPS or subjected to cecal-ligation and puncture (CLP)-induced polymicrobial sepsis, reduced serum TNF-α, and IL-1β levels, and increased survival." (PMID 34073678, 2021). "Corresponding to in vitro experiments, we used a mouse model of sepsis induced by CLP to further study the effects of circPTK2, miR-181c-5p and HMGB1 on mouse hippocampal neuronal apoptosis and cognitive dysfunction." (PMID 33952191, 2021). "However, the effects of HMGB1/RAGE on cell pyroptosis in sepsis-induced ALI remain unclear." (PMID 34747306, 2021). "Additionally, although the HMGB1/RAGE signaling still remains a potential yet promising therapeutic target in SAE, more studies will be required before we know what the functions of RAGE in critical organ disorder implicated in the etiopathogenesis of sepsis and SAE." (PMID 34867376, 2021). "Naringin reduces the release of TNF-α and HMGB1 from LPS-stimulated macrophages and improves survival in a CLP-induced sepsis mice." (PMID 33925132, 2021). "CircTLK1 sponged miR‐17‐5p to facilitate oxidative stress–mediated mtDNA damage, mitochondrial dysfunction and subsequent apoptosis in sepsis‐induced cardiomyopathy in vitro and in vivo via activating PARP1/HMGB1 axis." (PMID 34410682, 2021). "Wogonin was found to exert protective role in endothelial cells through inhibition of high mobility group box 1 (HMGB1) in LPS‐ and CLP‐induced sepsis and reduced sepsis‐related mortality in mice." (PMID 33982381, 2021). "Therefore, targeting HMGB1 may serve as a promising therapeutic strategy for sepsis-induced AKI." (PMID 34250012, 2021). "The HMGB-1, MyD88, TLR4, and NF-κB mRNA expressions were upregulated in the sepsis groups than in the NC group." (PMID 33859538, 2021). "To summarize, this research indicated that berberine targets HMGB1/RAGE signaling to inhibit microglia-stressed A1 astrocyte and neo-neuron decline, which consequently alleviates sepsis-induced cognitive impairment." (PMID 34867376, 2021). "RAGE can interact with HMGB1, and a previous study found that the RAGE pathway participated in the actions of DEX on sepsis-stimulated ALI in rats." (PMID 34747306, 2021). "These attributes render HMGB1 a late mediator of inflammation and hence an important target for potential therapies of inflammatory diseases such as ARDS and sepsis." (PMID 33293898, 2020).
Sepsis (continued). "This evidence suggests that sesamin can suppress the HMGB1/TLR-4/IL-33 signalling pathway, the activation of which is possibly involved in the in vitro LPS-induced sepsis model." (PMID 32893702, 2020). "High-mobility group box 1 (HMGB1) protein, when released, has been shown to promote inflammation in many occasions including sepsis." (PMID 33343575, 2020). "One of the important DAMPs is HMGB1 - a DNA binding protein that can be released from damaged cells under stress and activate tubular epithelial cells by interacting with TLR4 in sepsis." (PMID 33362762, 2020). "The findings were consistent between the in vitro and in vivo models; both pre- and post-transcriptional levels of HMGB1, TLR4, and IL-33 were significantly downregulated in the sesamin-treated sepsis group." (PMID 32893702, 2020). "HMGB1 forms a complex with DNA, and the HMGB1-DNA complex binds to receptor for advanced glycation end products (RAGE), which is a multi-ligand receptor on cell membrane involved in cancer, sepsis and other diseases." (PMID 32612147, 2020). "When HMGB1 protein expression in lung and liver tissues was assessed using Western blot assays, CLP-induced sepsis was found to result in strong immunoreactivity." (PMID 32943679, 2020). "High-mobility group box-1 (HMGB1), a ubiquitous nuclear protein, acts as a late mediator of lethality when released extracellularly during sepsis." (PMID 32328059, 2020). "A ubiquitous nuclear protein HMGB1 is released by activated macrophages/monocytes in late stages of SARS-CoV-2 infection, and functions as a late mediator of lethal endotoxaemia and sepsis." (PMID 32629817, 2020). "Our recent study discovered that high mobility group box 1 (HMGB1, a late mediator of sepsis) signals via receptor for advanced glycation end products (RAGE) to increase lung ILC2 by enhancing ILC2 proliferation and suppressing ILC2 death." (PMID 33193374, 2020). "HMGB1/PTEN/β-catenin signaling, as a novel pathway, plays an important role in sepsis-induced lung injury." (PMID 32412059, 2020). "Western blot analysis further confirmed that miR-22-3p overexpression significantly down-regulated the expression of PTEN, HMGB1, p-p65 and TLR4 in sepsis-induced acute renal injury rat models." (PMID 32412059, 2020). "Treatment with metformin decreased murine sepsis score (MSS), lactate, platelet lymphocyte ratio (PLR),and high mobility group box (HMGB1) levels." (PMID 32779431, 2020). "We studied the effect of TA-8 on HMGB1 by LPS-induced RAW264.7 inflammatory model and intraperitoneal injection of LPS-induced mouse sepsis model." (PMID 32153412, 2020). "The high-mobility group box 1 (HMGB1) protein is a nuclear factor and a late mediator of inflammation in sepsis." (PMID 31316298, 2019). "By identifying the regulatory pathway of HMGB1/PTEN/β-catenin signaling on Treg induction, our studies provide the rationale for novel therapeutic strategies for treating sepsis-induced lung injury." (PMID 31402909, 2019). "LncRNA HOX transcript antisense RNA (HOTAIR) has a high expression in sepsis-induced AKI, which facilitates the apoptosis of HK-2 cells in AKI via the miR-22/high mobility group box 1 (HMGB1) pathway." (PMID 31658856, 2019). "Therefore, understanding the relationship between cerebral HMGB1 and the activity of these pathways that cover both the central and peripheral systems will undoubtedly strengthen our knowledge of its role in the development of sepsis and provide more targets for treating septic cases." (PMID 30881224, 2019). "Taken together, these findings indicate a potential mechanism by which disruption of HMGB1/PTEN axis activates β-catenin signaling and promotes TGF-β, which contributes to the induction of CD4+CD25+Foxp3+ Tregs during lung injury in sepsis." (PMID 31402909, 2019). "High mobility group box-1 (HMGB1), a cytokine central to sepsis pathophysiology, has been identified as an important mediator of post-sepsis neurological manifestations." (PMID 31892321, 2019).
Sepsis (continued). "Moreover, HMGB1 contributes to cell migration and proliferation, cell differentiation and tissue regeneration, taking part in different pathophysiological processes and diseases, such as sepsis, arthritis, cancer, atherosclerosis, diabetes and cardiovascular diseases." (PMID 31835864, 2019). "Accumulated evidence show that the NLRP3 inflammasome also mediates the release of high mobility group box 1 (HMGB1), a late mediator of lethal sepsis, and contributes to the pathogenesis of septic shock." (PMID 30134814, 2018). "High mobility group box-1 protein (HMGB1), an important DAMP molecule, has been demonstrated to be a late pro-inflammatory mediator of sepsis." (PMID 29520271, 2018). "In previous studies on HMGB1, TNF-α and IL-6 were often used for reference and comparison with HMGB1, especially in studies on sepsis." (PMID 30157804, 2018). "Another novel result in our study is that the recombinant GSTP protein significantly increases the survival rate of CLP mouse and decreases the level of mouse serum HMGB1, which strongly suggests that recombinant GSTP protein is potential for sepsis therapy." (PMID 29520271, 2018). "Transcutaneous vagus nerve stimulation (t-VNS) has been shown to attenuate levels of the inflammatory mediator high mobility group box 1 (HMGB1) and improve survival in a murine sepsis model." (PMID 30057605, 2018). "Several DAMPs have been shown to correlate with sepsis morbidity and mortality including S100A8/A9, high-mobility group box-1 (HMGB1), mitochondrial DNA, nuclear DNA, histones and heat shock proteins (HSP)." (PMID 30459764, 2018). "Multiple studies have now evaluated blood HMGB-1 concentrations in dogs with GDV, pyometra and sepsis." (PMID 30105229, 2018). "In a separate study, P5 was shown to inhibit hemichannel-mediated ATP and high mobility group box 1 (HMGB1) release from cultured macrophages, and improved animal survival in models of sepsis and hepatic ischemia-reperfusion injury." (PMID 29601539, 2018). "The knockdown of Beclin1 has been shown to attenuate HMGB1-mediated release of TNF-α and IL-6 in lethal sepsis via inhibiting NF-kB18." (PMID 30478280, 2018). "In vivo experiments showed that there was a physical interaction between SIRT1 and HMGB1 in the nucleus and that SIRT1 regulated the acetylation level of HMGB1 in response to sepsis-related liver injury." (PMID 30533222, 2018). "We found that Gstp−/− mice displayed a higher mortality rate, severer acute lung injury and higher HMGB1 release level than wild type C57BL/6 mice after CLP surgery, which first demonstrated that GSTP acted as a key negative regulator in sepsis development." (PMID 29520271, 2018). "From the present study, antagonism of brain HMGB1 was effective in decreasing serum S100β and NSE levels, which implicating a potential therapeutic role of targeting HMGB1 in ameliorating sepsis induced brain dysfunction." (PMID 29190939, 2017). "In vivo, preclinical animal studies of inflammatory diseases such as sepsis revealed that GLY inhibits expression, extracellular secretion, and cytokine activity of HMGB1 and other pro-inflammatory cytokines." (PMID 29064403, 2017). "HMGB1 is the typical DAMP molecule, and it is involved in the setting of both sepsis and sterile inflammation." (PMID 29200665, 2017). "Hence the role of HMGB-1 in sepsis and patient outcome remains unclear." (PMID 28286376, 2017). "The apoptosis was diminished when HMGB1 was inhibited, as evidenced by less positive cells of TUNEL staining than the sepsis groups." (PMID 29190939, 2017). "APC also has anti-inflammatory properties, interfering especially with the activation of complement and the inactivation of high mobility group box 1 (HMGB1), a late phase death mediator in severe sepsis." (PMID 28271063, 2017). "Sepsis is a serious clinical syndrome, which is mediated by an early (such as TNF-α and IL-1) and late (such as HMGB1) pro-inflammatory cytokine response to infection." (PMID 27980458, 2016).